ARRB1 (arrestin beta 1)
Diseases named in the same sentence as ARRB1 in open-access papers (continued):
Sharing a sentence is not in itself a finding about the gene and the disease.
glioblastoma (5 papers, 2016 to 2025). The most malignant astrocytic tumor (WHO grade IV). "In glioblastoma, knockdown of ARRB1 decreases cell viability, metastasis and glycolysis by suppressing Src signaling." (PMID 33753990, 2021). "Indeed, ARRB1 under‐expression has been documented (in some cases along with that of miR‐326) in adult and pediatric gliomas and glioblastomas." (PMID 32920979, 2021). "TOP2A, COL4A1 and PXDN were significantly upregulated and ANK3, ARRB1 and ANO4 markedly downregulated in glioblastoma compared to controls." (PMID 32962742, 2020).
ovarian carcinoma (5 papers, 2020 to 2025). A malignant neoplasm originating from the surface ovarian epithelium. "The prognostic role of COL1A1, FN1, EDN1 (ET-1) and ARRB1 (β-arr1) gene expression was evaluated using the Kaplan–Meier plotter database and clinical ovarian cancer tissue samples." (PMID 39985042, 2025). "For ovarian cancer, ARRB1 is activated by ET-1R and cooperates with p300 to participate in the interaction between HIF-1α, which enhances the transcription of genes required for tumor cell invasion and angiogenesis." (PMID 33753990, 2021). "For ovarian cancer, the recruitment of ARRB1 showed the remarkable ability as a checkpoint converging pathway on β-catenin signaling to promote the invasion and metastasis of ovarian cancer cells." (PMID 33753990, 2021). "However, research in ovarian cancer suggested that ARRB1 is required for endothelin‐1‐induced NF‐κB activation." (PMID 32445435, 2020). "Therefore, TCGA data were used to analyze the expression of β-arrestin genes ARRB1 and ARRB2 and the survival of patients with ovarian cancer." (PMID 36969037, 2023).
depression (4 papers, 2013 to 2024). "Single nucleotide polymorphisms (SNP) of ARRB1 have been studied principally in the neuropsychiatric contexts of nicotine dependence and depression." (PMID 36386175, 2022). "A reduction in Arrb1 levels has been linked with the physiopathology of mood disorders (e.g., major depression)." (PMID 24066056, 2013). "Given that ARRB1 mRNA and β-arrestin 1 protein levels have been previously associated with depression and ATD treatment, variants annotated as likely to lie in a functional element—and thus be more likely to impact ARRB1 expression or β-arrestin function—were prioritized using RegulomeDB." (PMID 36386175, 2022). "Arrb1 mutation may affect the response of patients with depression to antidepressant therapy." (PMID 39135796, 2024). "Additionally, this study leveraged functional annotations to select and prioritize variants with likely functional consequences on ARRB1 expression for analysis since reduced β-arrestin 1 levels have been previously associated with depression severity and the response to ATD treatment." (PMID 36386175, 2022). "The present study showed that multiple pontine genes, including Anxa1, Serpinf1, Arrb1, Cplx2, Nrg1, and Psen1 were altered in a model of depression." (PMID 39135796, 2024). "Lower ARRB1 mRNA and β-arrestin 1 protein levels have been observed in murine models of depression, as well as in human mononuclear leukocytes of depressed patients, compared to healthy controls." (PMID 36386175, 2022). "Introduction: β-arrestin 1, a protein encoded by ARRB1 involved in receptor signaling, is a potential biomarker for the response to antidepressant drug (ATD) treatment in depression." (PMID 36386175, 2022).
glioma (4 papers, 2016 to 2023). A benign or malignant brain and spinal cord tumor that arises from glial cells (astrocytes, oligodendrocytes, ependymal cells). "SOX6 was found to specifically expressed either in foetal brain or gliomas, but faintly in the adult brain, which again indicates that it might have a role in transformation by repressing various tumour-suppressive targets like the ARRB1 locus." (PMID 27871300, 2016). "To further clarify the pathological importance of AEP/tDDX3X–mediated ARRB1-Δexon 13 splicing in cancer, we performed Western blotting and verified the significantly higher protein levels of AEP and tDDX3X in HGG and recurrent glioma (RecG) than in normal tissues and LGG." (PMID 37988165, 2023).
lung adenocarcinoma (4 papers, 2018 to 2022). A carcinoma that arises from the lung and is characterized by the presence of malignant glandular epithelial cells. "However, in another study recruiting 105 patients with surgically resected lung adenocarcinoma, overexpression of ARRB1 was considered to be associated with an unfavorable prognosis in lung adenocarcinoma." (PMID 36213111, 2022). "A study conducting microarray analysis in ARRB1-depleted lung adenocarcinoma cell line A549 versus parental A549 cells has shown that nicotine stimulation drives expression of Stem Cell Factor (SCF) in an ARRB1-mediated fashion." (PMID 33297302, 2020).
non-alcoholic steatohepatitis (4 papers, 2020 to 2025). "For example, in mouse models of non-alcoholic steatohepatitis, downregulated ARRB1 in hepatocytes impairs the transport of GDF15 precursor to the Golgi apparatus for cleavage and maturation, thereby promoting intracellular lipid accumulation." (PMID 40677718, 2025). "A recent study showed that ARRB1 inhibited nonalcoholic steatohepatitis progression by promoting growth differentiation factor 15 maturation." (PMID 34455423, 2021). "Although previous studies have reported the protective role of ARRB1 in many liver diseases, such as non-alcoholic steatohepatitis, liver ischemia/reperfusion injury, and lipopolysaccharide-induced acute liver injury, there is no report about the role of ARRB1 in APAP-induced liver injury." (PMID 38252352, 2024). "Also, our recently study revealed that ARRB1 exerts protective function in the pathology of non‐alcoholic steatohepatitis (NASH) by promoting GDF15 maturation, whereas the expression and function of ARRB family members in the process of hepatic I/R injury still remain unknown." (PMID 32445435, 2020).
non-small cell lung carcinoma (4 papers, 2020 to 2026). A group of at least three distinct histological types of lung cancer, including non-small cell squamous cell carcinoma, adenocarcinoma, and large cell carcinoma. "A report that corroborates with our results suggests that the deletion of ARRB1 expression predicted an unfavorable prognosis in non-small cell lung cancer." (PMID 36213111, 2022). "In non-small cell lung cancer (NSCLCs), nicotine stimulation induces mitogenic signaling in an ARRB1 depended fashion." (PMID 33297302, 2020).
bladder cancer (3 papers, 2019 to 2021). "In the current work, we investigated the role of ARRB1 in regulating the metabolic preference of cancer stem cell (CSC)-like cells in bladder cancer (BC)." (PMID 33920080, 2021). "In the present work, we analyzed for the first time the role of adapter protein ARRB1 in regulating the metabolic preference of CSC-like bladder cancer cells." (PMID 33920080, 2021). "In contrast, depletion of ARRB1 in bladder cancer cells abrogated expression of CD44 and resulted in significantly reduced protein levels of Bmi1." (PMID 33297302, 2020). "It is noteworthy that ARRB1 functions as a tumor suppressor in medulloblastoma which is in contrast with its role in other cancers such as bladder cancer and leukemia." (PMID 33297302, 2020). "ARRB1 and ARRB2 appear to have opposing functions in regulating stem cell properties in bladder cancer." (PMID 33297302, 2020). "While the role of ARRB1 in regulating Bmi-1 in leukemia has not been established, there is evidence that ARRB1 is essential for maintaining Bmi1 driven self-renewal in bladder cancer." (PMID 33297302, 2020).
colitis (3 papers, 2017 to 2024). Inflammation of the colon. "Our study demonstrated that ARRB1 deficiency impaired the intestinal tight junctions barrier through mitochondrial dysfunction accompanied by lower adenosine triphosphate (ATP) production and increased oxidative stress in colitis mice." (PMID 39246845, 2024). "MFN2 expression was reduced in colitis, and ARRB1 deficiency exacerbated this decrease." (PMID 39246845, 2024). "Next, we addressed whether the susceptibility of ARRB1 deficiency to colitis was due to an intestinal epithelial barrier defect." (PMID 39246845, 2024). "A previous study found the deficiency of ARRB1 protects against experimental colitis." (PMID 39246845, 2024). "Our previous study found that ARRB1 is involved in COX-1/PGE2/EP4-mediated mucosal protection in colitis." (PMID 39246845, 2024). "The serum concentration of FD4 in experimental colitis was significantly higher in ARRB1 KO mice than in wild-type (WT) mice, indicating that ARRB1 deficiency contributed to increased intestinal permeability." (PMID 39246845, 2024). "Western blotting showed that the mitophagy-associated proteins PINK1, Parkin, and LC3B were significantly upregulated in experimental colitis, but ARRB1 KO inhibited the upregulation of these proteins." (PMID 39246845, 2024). "In conclusion, the KO of ARRB1 resulted in mitochondrial dysfunction and a disrupted intestinal barrier in colitis." (PMID 39246845, 2024). "We identified that ARRB1 protected the intestinal tight junction barrier against experimental colitis in vivo." (PMID 39246845, 2024). "According to scanning electron microscopy, the tight junction between cells on the apical side of the colonic epithelium was significantly more damaged in ARRB1 KO mice than in WT mice with colitis." (PMID 39246845, 2024). "In ARRB1 KO mice, colitis induced significant exhaustion of glutathione and elevation of malondialdehyde, which indicated a deficit in antioxidant capacity." (PMID 39246845, 2024). "Dextran sulfate sodium-induced colitis was performed in ARRB1 knockout and wild-type mice." (PMID 39246845, 2024). "However, we previously demonstrated that ARRB1 mediated mucosal protection by COX-1/PGE2/EP4 in colitis." (PMID 39246845, 2024). "The promote relationships between TNF-α and Vascular Endothelial Growth Factor-C (VEGF-C), ARRB1 and VEGF-C has been confirmed in many diseases including pulmonary hypertension, colitis and gallbladder cancer 22-24." (PMID 33753990, 2021). "ARRB1-dependent signaling in hematopoietic and nonhematopoietic cells differentially regulates colitis pathogenesis." (PMID 39246845, 2024). "Furthermore, it has not yet been established whether ARRB1 regulates epithelial barrier function in colitis." (PMID 39246845, 2024). "Additionally, in intestinal epithelial cells of colitis, TNF-α/ARRB1-dependent signaling in hematopoietic and non-hematopoietic cells differentially regulates colitis pathogenesis in modulating MAPK pathways." (PMID 33753990, 2021).
colorectal cancer (3 papers, 2017 to 2025). A primary or metastatic malignant neoplasm that affects the colon or rectum. "Among them, ARRB1 showed the highest percentage of expression in colorectal cancer, while showing lower levels of expression in most tumor tissues." (PMID 36213111, 2022). "Alternatively, ARRB1 has also been shown to enhance the activation of EGFR in colorectal cancers leading to increased mitogenic signaling." (PMID 28596572, 2017). "For instance, studies have demonstrated involvement of ARRB1, MGST1, and TTPAL in colorectal cancer, leading to increased cancer cell proliferation and subsequent poor prognosis." (PMID 40186098, 2025).
experimental autoimmune encephalomyelitis (3 papers, 2016 to 2021). An autoimmune demyelinating disease of the central nervous system that is produced experimentally in animals by the injection of homogenized brain or spinal cord in Freund's adjuvant. "For instance, high ARRB1 expression is related to the pathogenesis of experimental autoimmune encephalomyelitis and multiple sclerosis." (PMID 27642302, 2016). "For example, in an experimental autoimmune encephalomyelitis (EAE) mouse model, ARRB1 knockout alleviates disease phenotypes, whereas ARRB2 deficiency exacerbates EAE symptoms." (PMID 33686256, 2021). "Studies have found an obvious increased expression of Arrb1 in CD4+ T cells from MS patients; Further, mice which lack the Arrb1 gene are presented to be more likely to survive from experimental autoimmune encephalomyelitis, which is a classical mouse model for multiple sclerosis." (PMID 27669210, 2016).
gallbladder cancer (3 papers, 2021 to 2024). "For instance, in one study, ARRB1 protein expression was found to be upregulated in gallbladder cancer (GBC) tissue and correlated with aggressive clinicopathological features and poor prognosis in patients." (PMID 36213111, 2022). "For these genes, some researchers have found that ARRB1 can promote the activation of the TAK1/MAPK pathway to promote the progression of gallbladder cancer, and ARHGAP4 can be targeted by miR-939-5p, thereby promoting the invasion and metastasis of pancreatic cancer." (PMID 38688945, 2024).
multiple sclerosis (3 papers, 2016 to 2017). A progressive autoimmune disorder affecting the central nervous system resulting in demyelination. "Accordingly, the enhanced expression of Arrb1 will be associated with the multiple sclerosis." (PMID 27669210, 2016). "Of note CD4+ T cells from patients with multiple sclerosis had much higher Arrb1 expression and miR-326 expression was highly correlated with disease severity in patients with multiple sclerosis." (PMID 28298929, 2017).
acromegaly (2 papers, 2022 to 2024). Acromegaly is an acquired disorder related to excessive production of growth hormone (GH) and characterized by progressive somatic disfigurement (mainly involving the face and extremities) and systemic manifestations. "Tumor expression of particular genes was found of prognostic/predictive value in acromegaly patients, These genes include basically CDH1 and SSTR2 but also CDKN1B SNAI2, FLNA, ARRB1, SNAI1 RORC ESRP1, and MKI67." (PMID 39497133, 2024).
adenoma (2 papers, 2020 to 2025). A neoplasm arising from the epithelium. "In adenoma, ARRB1, CTBP1 and CTBP2 were overexpressed, suggesting their involvement in early tumorigenesis, whereas in CIS, RPS3A and COL4A5 were overexpressed, suggesting their involvement in the transition from benign to malignant stage." (PMID 40362431, 2025). "ARRB1 was also validated as significantly upregulated (p-value < 0.0001) in the adenoma samples compared to adenocarcinoma." (PMID 40362431, 2025). "Among the identified molecular targets, ARRB1 was validated using RT-qPCR for adenoma, COL4A5 and RPS3A for CIS, and COL1A2 and MED10 for adenocarcinoma." (PMID 40362431, 2025). "Additionally, the involvement of ARRB1 in the Wnt/beta-catenin signaling pathway, a hallmark driver of CRC and the most representative canonical signaling pathways, suggests its potential as an early biomarker for the development of adenomas." (PMID 40362431, 2025). "ARRB1, CTBP1 and CTBP2 were genes identified based on the top 20 frequently occurring genes and are upregulated in adenoma samples." (PMID 40362431, 2025). "Comparative analysis between adenoma with adenocarcinoma samples showed that ARRB1, CTBP1 and CTBP2 are overexpressed in adenoma." (PMID 40362431, 2025). "ARRB1 (p = 2.79 × 10−5), CTBP1 (p = 1.33 × 10−5) and CTBP2 genes (p = 0.0002) exhibited notable upregulation in adenoma, whereas COL1A2 (p = 0.0075), CEBPZ (p = 0.0057), MED10 (p = 0.0196) and PAWR genes (p = 0.00215) showed significant upregulation in adenocarcinoma." (PMID 40362431, 2025).
Arthritis (2 papers, 2019 to 2020). Inflammation of a joint. "In addition, deficiency of ARRB1 impairs inflammatory response thus ameliorating collagen‐induced arthritis." (PMID 32445435, 2020).
Cerebral ischemia (2 papers, 2023 to 2024). Restriction of arterial blood supply to the brain associated with insufficient oxygenation to support the metabolic requirements of the tissue. "ARRB1 regulates BECN-dependent auto-phagosome formation to mediate neuroprotection in cerebral ischemia." (PMID 39246845, 2024). "Deletion of Arrb1 significantly inhibited autophagy and induced neuronal apoptosis and necrosis in a model of cerebral ischemia." (PMID 37122736, 2023). "The deletion of ARRB1 did not affect cerebral ischemia-induced inflammation and oxidative stress but markedly suppressed autophagy and induced neuronal apoptosis/necrosis." (PMID 39246845, 2024).
heart failure (2 papers, 2014 to 2023). Inability of the heart to pump blood at an adequate rate to meet tissue metabolic requirements. "ARRB1 appears to be cardiotoxic in that genetic deletion of ARRB1 in the heart showed therapeutic effects in heart failure, whereas ARRB2 was found to be cardioprotective against cardiac inflammation and apoptosis." (PMID 35960440, 2023).
Hepatic fibrosis (2 papers, 2021 to 2024). The presence of excessive fibrous connective tissue in the liver. "ARRB1 has consistently been associated with hepatic fibrosis." (PMID 39301288, 2024). "In a constitutive ARRB1 knockout mouse model of hepatic fibrosis, collagen deposition in the liver was decreased by 50%." (PMID 39301288, 2024).
liver disease (2 papers, 2024 to 2025). "Interestingly, many of the genes linked to the differentially methylated CpGs have been associated with liver disease progression (eg, DCP2, TRPV3, ARRB1, KCNIP4, MIR10A) and cancer formation or progression (eg, MTHFR, GRIK2, GSN, HOX3, KCNMA1)." (PMID 40275933, 2025). "Despite numerous studies emphasizing the significance of ARRB1 in liver diseases, there is a lack of research focusing on the role of ARRB1 in APAP-induced liver injury." (PMID 38252352, 2024).
lung squamous cell carcinoma (2 papers, 2019 to 2025). "The molecular characterization of the activity of the RNA-binding protein LSM12 and its interplay with SAMD4A reveals that LSM12 promotes lung squamous cell carcinoma progression by regulating alternative splicing of the ARRB1 gene." (PMID 40425760, 2025).
Obesity (2 papers, 2022). Accumulation of substantial excess body fat. "The transgene overexpression of ARRB1 inhibited diet-induced obesity and improved glucose tolerance and systemic insulin sensitivity." (PMID 35159307, 2022). "Comparing the body weight of AAV-injected Sim1-cre mice versus AAV-injected wild-type littermates, we found that overexpression of Snca and Igsf8 caused an exacerbation of HFD-induced obesity, whereas overexpression of Spata2, Pole4, Fndc4, Smim12, or Arrb1 had no impact on body weight." (PMID 36175420, 2022).
oral cancer (2 papers, 2017 to 2020). "In the present study, the inhibitory role of the alpha mangostin on the genes implicated in Oral cancer namely CALM3, ARRB1, HTT, and FLNAwas investigated through molecular docking techniques." (PMID 33214751, 2020). "Background and Aim: The genes ARRB1, FLNA, CALM3, and HTT are commonly expressed in oral cancer and have been hypothesized to be involved in the carcinogenic pathway." (PMID 33214751, 2020).
preeclampsia (2 papers, 2021). Preeclampsia is a hypertensive disorder of pregnancy that is characterized by new-onset hypertension with proteinuria presenting after 20 weeks of gestation, and depending on mild or severe forms may initially present with severe headache, visual disturbances, and hyperreflexia. "ERK1/2-stimulated signaling and levels of dysfunctional ARRB1 are increased on vascular cells of the experimental AT1R-B2R-induced preeclampsia model, and on placentas of pregnancies complicated with preeclampsia." (PMID 34685589, 2021). "Consequently, during the pathogenesis of preeclampsia, inflammation-induced AT1R-B2R protein complexes stimulate ARRB1 dysfunction, which in turn promotes pathological AT1R-B2R protein aggregation by protein stabilization." (PMID 34685589, 2021).
primary biliary cirrhosis (2 papers, 2020 to 2022). "The most recent findings further indicate that ARRB1 can enhance the progression of primary biliary cirrhosis by regulating the function of autoimmune T cells." (PMID 36123690, 2022).